ASMER1 (adipocyte associated metabolic related lncRNA 1)
Synonyms: ENST00000418954; ASMER-1; LINC02246
Gene: Long non-coding RNA gene on chromosome 21 (14,816,838 to 15,064,771, reverse strand). Ensembl gene ENSG00000281903.
Diseases named in the same sentence as ASMER1 in open-access papers:
ASMER1 is named in the same sentence as 2 diseases in open-access papers, as found by Europe PMC text mining. Sharing a sentence is not in itself a finding about the gene and the disease.
ASMER1 shares sentences with these, for which no sentence is quoted: Abdominal obesity (1 paper); Obesity (1).